KIR2DL3 (killer cell immunoglobulin like receptor, two Ig domains and long cytoplasmic tail 3)
Diseases named in the same sentence as KIR2DL3 in open-access papers (continued):
Sharing a sentence is not in itself a finding about the gene and the disease.
leukemia (2 papers, 2016 to 2021). A malignant (clonal) hematologic disorder, involving hematopoietic stem cells and characterized by the presence of primitive or atypical myeloid or lymphoid cells in the bone marrow and the blood. "To document the impact of allogeneic HLA class I molecules on the modulation of KIR2DL3+ T cell function and in absence of well-established leukemia model, we focused our investigations on HLA-A2-pp65 specific T lymphocytes." (PMID 34349169, 2021). "KIR phenotypes analysis in Belgian leukemia patients indicated significantly higher frequencies of inhibitory KIR2DL1, KIR2DL2, and KIR2DL3 genes, suggesting their contribution for the lack of antitumor responses of NK cells." (PMID 27708784, 2016).
neuroblastoma (2 papers, 2023 to 2025). Neuroblastoma (NB) is the most common solid, extracranial childhood tumor. "Additionally, patients with early-stage neuroblastoma showed higher expression of KIR2DS3 and lower expression of KIR2DL3 compared to patients with metastatic disease." (PMID 40244151, 2025). "Although the patient sample was small, these results suggest that KIR2DL3 and KIR2DS3 may play a role in neuroblastoma development." (PMID 40244151, 2025).
tuberculosis (2 papers, 2012 to 2021). A chronic, recurrent infection caused by the bacterium Mycobacterium tuberculosis. "In the context of tuberculosis, a higher prevalence of KIR2DL3 among TB patients has been observed in two independent studies." (PMID 22788220, 2012).
adenovirus infection (1 paper, 2017). "Interestingly, expression of HLA-Cw*0702 is also relatively protected following adenovirus infection where it plays an important role in engaging the inhibitory protein KIR2DL3 on NK cells." (PMID 29312307, 2017).
anemia (1 paper, 2012). A reduction in the number of red blood cells, the amount of hemoglobin, and/or the volume of packed red blood cells. "In addition, the results from our study suggest that anemia during pregnancy might be regulated by KIR genes, and malaria infection could have a selective pressure on KIR2DL2, KIR2DL3 and other relevant KIR genes." (PMID 22715396, 2012).
borderline leprosy (1 paper, 2019). A form of leprosy in which there are clinical manifestations of both principal types (lepromatous and tuberculoid). "In conclusion, we highlight the new associations found in this study, where KIR2DL2/2DL2/C1/C2+ and KIR2DL3/2DL3/C1/C1+ are indicated to be important risk factors for developing lepromatous and borderline leprosy, respectively." (PMID 31525196, 2019). "These are unprecedented results in which KIR2DL2/KIR2DL2/C1/C2 and KIR2DL3/2DL3/C1/C1 indicated a risk for developing lepromatous and borderline leprosy, respectively." (PMID 31525196, 2019).
chronic hepatitis (1 paper, 2017). An active inflammatory process affecting the liver for more than six months. "Previous reports have suggested an association between KIR2DL3 and clearance of hepatitis C virus with subsequent protection from chronic hepatitis, and liver damage." (PMID 29149205, 2017).
co-infection (1 paper, 2012). "The results suggest that inhibitory KIR2DL2 and KIR2DL3, which are alleles of the same locus, play a role in the inverse effects on PM alone and PM/HIV co-infection and the effect of KIR gene content polymorphisms on PM in HIV-1 positive women is dependent on high CD4 cell counts." (PMID 22715396, 2012). "Collectively, the results suggest that inhibitory KIR2DL2 and KIR2DL3, which are alleles of the same locus, play a role in the inverse effects on PM and PM/HIV co-infection, and the effect of KIR gene content polymorphisms on PM in HIV-1 women is dependent on high CD4 counts." (PMID 22715396, 2012). "Collectively, these results suggest that inhibitory KIR2DL2 and KIR2DL3, which are alleles of the same locus, play a role in the inverse effects on PM and PM/HIV co-infection and the effect of KIR genes on PM in HIV positive women is dependent on high CD4 cell counts." (PMID 22715396, 2012).
hepatitis B infection (1 paper, 2017). "Further studies are needed either to establish an independent effect of KIR2DL3 in hepatitis B infection or to confirm the protective effect of KIR2DL3/HLA-C combinations." (PMID 29149205, 2017).
Hodgkins lymphoma (1 paper, 2015). A heterogeneous group of malignant lymphoid neoplasms of B-cell origin characterized histologically by the presence of Hodgkin and Reed-Sternberg (HRS) cells in the vast majority of cases. "Genes KIR2DL1, KIR2DL3, KIR2DL5, and KIR2DS3/S5 were also present in our patients in haplotype motifs other than the classic cA01 (or KIR2DL1 and -2DL3) and cB01 (for the KIR2DL1, KIR2DL5, KIR2DS3, and KIR2DS5), as suggested for certain Hodgkin's lymphomas." (PMID 26495028, 2015).
leprosy (1 paper, 2019). Leprosy is a chronic infectious disease affecting primarily the skin and peripheral nervous system. "In addition, it has already been shown that KIR2DL2 receptor binds stronger than KIR2DL3 to HLA-C ligands, which could explain why we have the association between KIR2DL2 and LL clinical form, while KIR2DL3 associates with borderline leprosy, a less severe form of the disease." (PMID 31525196, 2019).
lymphoid neoplasm (1 paper, 2020). A neoplasm composed of a lymphocytic cell population which is usually malignant (clonal) by molecular genetic and/or immunophenotypic analysis. "In lymphoid neoplasms, there was a slightly increased KIR2DL3 expression compared to myeloid malignancies." (PMID 33138211, 2020). "Considering the underlying diagnosis of the recipient, the most striking effects were found in KIR2DL3, where we detected obvious differences among myeloid and lymphoid neoplasms (in the second and third month after HSCT p < 0.05)." (PMID 33138211, 2020).
lymphoproliferative disorder (1 paper, 2015). "Furthermore, results suggest that KIR2DL3 was more related with lymphoproliferative disorders when the KIR2DL2 gene was also present (Cent 2 compared to Cent 1)." (PMID 25700262, 2015).
measles (1 paper, 2023). A highly contagious viral infection caused by the measles virus. "Allograft rejection, fatty acid elongation, and mismatch repair were significantly enriched in the high KIR2DL3 subgroup, but measles, type II diabetes mellitus, and viral protein interaction with cytokine and cytokine receptor were significantly enriched in the low KIR2DL3 subgroup." (PMID 37950194, 2023).
Sezary syndrome (1 paper, 2021). Sezary syndrome (SS) is an aggressive form of cutaneous T-cell lymphoma characterized by a triad of erythroderma, lymphadenopathy and circulating atypical lymphocytes (Sezary cells). "Overexpression of KIR2DL3 has been described in Sezary syndrome and MF, but its functional role in MF is not fully elucidated." (PMID 34204115, 2021).
syphilis (1 paper, 2025). A contagious bacterial infection caused by the spirochete Treponema pallidum. "Additionally, the KIR2DL3/HLA-C1C1 genotype is more common in healthy controls compared to patients with syphilis, suggesting a possible synergistic protective effect between HLA-C1 and KIR2DL3." (PMID 40244151, 2025).
thyroid cancer (1 paper, 2018). "However, none of the thyroid cancer cell culture supernatants altered the expression levels of NK cell inhibitory receptors such as killer cell immunoglobulin-like receptor (KIR)2DL1 and KIR2DL3." (PMID 30140269, 2018).
Trachoma (1 paper, 2014). "The data presented indicate that HLA-C genotypes are important determinants of conjunctival scarring in trachoma and that KIR2DL2/KIR2DL3 heterozygosity further increases risk of conjunctival scarring in individuals carrying HLA-C2." (PMID 24651768, 2014).
ulcerative colitis (1 paper, 2014). An inflammatory bowel disease involving the mucosal surface of the large intestine and rectum. "In this context, the frequency of KIR2DL1 and KIR2DL3 genotypes was shown to be lower in ulcerative colitis patients as compared to control individuals." (PMID 25310588, 2014).
tumor (24 papers, 2010 to 2025). "We also found that several genes, including TYROBP, CD1C, KIR2DL3, CD3G, and TARP, were significantly highly expressed in patients with a high tumor mutational burden." (PMID 35204406, 2022). "KIR2DL3 was expressed in 4.69 ± 0.29% and 4.35 ± 0.25% of non-tumor and GBM tissue, respectively." (PMID 37762486, 2023). "Additionally, an array of specific NK inhibitory markers, namely KIR2DL1, KIR2DL3, and KIR2DL4, were elevated, indicative of tumor-induced NK cell suppression." (PMID 40547037, 2025). "KIR2DL1 and KIR2DL2 expression did not demonstrate differences between GBM and non-tumor samples in TCGA database (p = 0.08 and 0.69, respectively), while KIR2DL3 expression demonstrated differences (p < 0.01)." (PMID 37762486, 2023). "We have previously generated transgenic mice expressing the human inhibitory receptor KIR2DL3 (TgKIR mice), which were crossed with RAG-1 KO animals that lack T and B cells (TgKIR-RAG1KO) to generate recipients for human tumor cells expressing the MHC class I molecule HLA-Cw3, a ligand for KIR2DL3." (PMID 34071607, 2021). "Interestingly, both inhibitory KIR (KIR2DL1, KIR2DL3 and KIR3DL1) and activating KIR (KIR2DS1 and KIR2DS4) were reduced in expression when effectors were exposed to tumor in the presence of TriKE." (PMID 32961861, 2020).
cancer (19 papers, 2012 to 2025). A tumor composed of atypical neoplastic, often pleomorphic cells that invade other tissues. "And the finding demonstrated a strong correlation between elevated levels of immune checkpoints and the SREBF1 in ACC, notably KIR2DL3, IL2RA, CD80, IFNG, BTN3A2, and IL1A, also IFNA1 wass significantly associated with SREBF1 in the majority of cancers." (PMID 40668814, 2025). "At the gene level, FDCSP (cancer cell migration and invasion), KIR2DL3 (immune response), SLC30A10 (antiapoptotic), MAB21L2, PCDH9 (cell adhesion), PEG3 (cell proliferation) were found to be highly expressed in the Lymph-node (LN)-positive samples." (PMID 37377901, 2023). "Immunostimulators KIR2DL1 and KIR2DL3 lack sufficient data in most cancers." (PMID 39830645, 2024). "Analysis of data from The Cancer Genome Atlas and Genotype‐Tissue Expression databases revealed that KIR2DL1, KIR2DL3 and KIR2DL4 expression were significantly upregulated in AML and associated with decreased overall survival (OS)." (PMID 38527290, 2024). "Inhibitory KIR (such as KIR2DL1, KILR2DL2, KIR2DL3 and KIR3DL1) interaction with its ligand may protect cancer cells from NK cell-mediated killing." (PMID 36817482, 2023). "In addition, the interactions of KIR2DL3 and FAM3C, and KLRB1 and CLEC2D were detected between cancer cells and T & NK cells." (PMID 37945567, 2023). "Also, we observed that USP5 was correlated with most immune inhibitors and immune stimulators except for KIR2DL1, KIR2DL3 and TNFSF18 in pan-cancer." (PMID 37268697, 2023). "Unlike HMGB1, IFNA1, IFNA2, IL-2, KIR2DL3, IL-13 and NCAPG2 demonstrated an intuitive correlation in only a few cancer types." (PMID 36776838, 2023).
infection (12 papers, 2011 to 2025). The state of being infected such as from the introduction of a foreign agent such as serum, vaccine, antigenic substance or organism. "Specifically, a positive association was observed between the risk of infection and the following genes: the inhibitory genes KIR2DL3 and KIR3DL1, along with the activating genes KIR2DS1 and KIR2DS4." (PMID 40244151, 2025). "Kermes suggests that the combination of KIR2DL3 + HLA-C1 genes with little inhibitory effect resolves infection with hepatitis C virus more efficiently." (PMID 37760846, 2023). "In Caucasians, patients with persistent hepatitis C virus (HCV) infection have a higher frequency of KIR2DL3 than those who have successfully cleared infection." (PMID 35874712, 2022). "The presence of KIR2DL3 in the child reflects an increased probability of protection against infection in the child (P<0.1)." (PMID 28225833, 2017). "Other studies in cohorts of injection drug users confirmed that exposed but uninfected individuals had a higher frequency of KIR2DL3 expression than drug users with chronic and resolved infections or healthy donors." (PMID 28567042, 2017). "Previous studies identified KIR2DS3 and HLA-C1+ KIR2DL3+, especially when in homozygous as NK cell-associated KIR genes at a higher frequency in patients who resolved infection compared with CHC patients." (PMID 25700262, 2015). "In the treatment cohort, IFN‐λ3/4 rs12979860 CC was protective in hepatitis C virus (HCV) G1 infection and KIR2DL3:HLA‐C1 in HCV G2/3." (PMID 26381047, 2015). "In a population from Burkina Faso, KIR2DL2, KIR2DL3, and KIR2DS2 are associated with chronic stages of HBV infection, while KIR3DL1, KIR3DL2, KIR2DS1, and KIR2DP1 are associated with immunity against the infection." (PMID 40244151, 2025). "KIR2DL3+ also plays inhibitory function but is weaker than KIR2DL2+, so KIR2DL3+ NK cells are more easily activated, which might inhibit the virus at the early stage of infection to prevent disease." (PMID 35874712, 2022). "In addition, IFN‐λ3/4 rs12979860 CC (P = 0.043, OR 3.11, 95% CI 1.04–9.32) and KIR2DL3:HLA‐C1 (P = 0.018, OR 4.90, 95% CI 1.32–18.25) were protective in HCV in genotype 1 infection and HCV genotype 2 or 3 infection, respectively." (PMID 26381047, 2015). "Notably, lack of HLA-C1 expression in KIR2DL3/2DS2+ SOT recipients or donors is associated with increased risk of CMV viremia, suggesting that KIR2DL3/HLA-C1 interactions may be protective during infection." (PMID 34358058, 2021).
infectious disease (1 paper, 2015). A disorder directly resulting from the presence and activity of a microbial, viral, or parasitic agent in humans. "Despite having similar ligands, KIR2DL2 and KIR2DL3 confer different levels of protection to infectious disease." (PMID 25359276, 2015).
KIR2DL3 also shares sentences with these, for which no sentence is quoted: AIDS (3 papers); hepatoblastoma (2); adenocarcinoma (1); adrenocortical carcinoma (1); autoimmune hepatitis (1); bladder urothelial carcinoma (1); cervical squamous cell carcinoma (1); Cirrhosis (1); endocervical adenocarcinoma (1); glioma (1); Graves disease (1); head and neck squamous cell carcinoma (1); Hepatitis (1); Hypertension (1); inflammatory bowel disease (1); influenza infection (1); LGL leukemia (1); liver cancer (1); lymph node metastasis (1); lymphoma (1); malignant pleural mesothelioma (1); metastatic melanoma (1); multiple sclerosis (1); myeloid leukemia (1); myeloid malignancies (1); myeloma (1); NK cell leukemia (1); non-small cell lung carcinoma (1); ocular toxoplasmosis (1); ovarian carcinoma (1).
A further 6 diseases each share a sentence with KIR2DL3 in 1 paper.